E2F1 (E2F transcription factor 1)
Diseases named in the same sentence as E2F1 in open-access papers (continued):
Sharing a sentence is not in itself a finding about the gene and the disease.
cervical carcinoma (56 papers, 2006 to 2025). A carcinoma arising from either the exocervical squamous epithelium or the endocervical glandular epithelium. "The released E2F1 transcription factor from p-Rb triggers the transcription of target DNA replication-associated genes to promote the G1/S transition thus allows cervical cancer cell proliferation." (PMID 33516252, 2021). "In cervical cancer, the high expression of E2F1 was associated with the enrichment of tumor suppressor genes such as E2F signaling pathway genes (p = 0.002) and the high expression of EREG was associated with TGF-beta (p < 1E−16) signaling pathway genes." (PMID 33723286, 2021). "We also found that upregulation of E2F1/2/7/8 is an independent prognostic factor for patient OS and that genetic alterations of E2Fs were associated with poor DFS in cervical cancer, indicating that dysregulation of E2F1/2/7/8 may be associated with progression of cervical cancer." (PMID 33061852, 2020). "Cdk1 is known as a transcriptional target of E2F1 and Sp1 proteins which is responsible for G1/S progression, and its overexpression has been stated in cervical cancer." (PMID 41516135, 2025). "It has been reported that miR-136 is downregulated in cervical cancer, suppresses tumor cell apoptosis and induces cell apoptosis by targeting E2F1." (PMID 38331752, 2024). "In cervical cancer cell lines, overexpression of E2F1 resulted in an increase in nc886 expression, whereas treatment with caffeine, an E2F1 inhibitor, led to a decrease in nc886 expression." (PMID 37239877, 2023). "Enhanced E2F7 expression is also found in many types of cancer and a predictor of poor prognosis, e.g., in OSCC and glioblastoma patients, and for E2F1/2/7/8 also in cervical cancer patients." (PMID 35063803, 2022). "FTO can control the m6A modification of E2F1 and Myc transcripts to regulate the proliferation and migration of cervical cancer cells." (PMID 36058934, 2022). "pointed out that upregulation of SKA3 elevated the expression of CDK4, p-Akt, Cdk2 cyclinE2, p-Rb, E2F1, and cyclinD1 in HeLa cells, thus promoting cervical cancer proliferation and migration." (PMID 34845974, 2021). "We found that ac-E2F1 K117 and K125 acetylation were elevated in cervical cancer compared with normal tissues." (PMID 33516252, 2021). "Here, we found overexpression or silence of circZFR separately increased or decreased p-Rb S807 and S608 phosphorylation ac-E2F1 K117 and K125 acetylation in cervical cancer cells." (PMID 33516252, 2021). "Of interest, the induction of RNASEH2A by E2F1 has been also reported in human papillomavirus cervical cancers." (PMID 33805806, 2021). "For example, FTO plays an important oncogenic role in regulating the proliferation and migration of cervical cancer cells through m6A modification that controls E2F1 and Myc transcription." (PMID 33952279, 2021). "DNA replication, G1/S transition, and cell proliferation were demonstrated to be an essential driving pathway for cervical cancer, with E2F1 representing the core transcription factor for regulating these pathways." (PMID 33516252, 2021). "First, MELK expression was activated by the HPV E6/E7 via E2F1 and was necessary for cervical cancer growth." (PMID 34671205, 2021). "We also assessed the prognostic import of E2F1/2/7/8 in patients with cervical cancer by analyzing clinicopathological data." (PMID 33061852, 2020). "After exploring mRNA expression levels of E2Fs in silico, we next attempted to confirm increased E2F1/2/7/8 protein levels in tumor tissue of patients with cervical cancer by IHC." (PMID 33061852, 2020). "Using multivariate analysis, we also confirmed E2F1/2/7/8 as independent prognostic factors for shorter OS of patients with cervical cancer." (PMID 33061852, 2020).
cervical carcinoma (continued). "In silico analysis showed that E2F1/2/7/8 were significantly overexpressed in cervical cancer, findings which were confirmed at the protein level using immunohistochemistry." (PMID 33061852, 2020). "In this study, we comprehensively explored the transcriptional expression of E2Fs in cervical cancer, finding that E2F1/2/7/8 are significantly overexpressed in this disease." (PMID 33061852, 2020). "E2F transcription factor 1 (E2F1) has been previously documented as a direct target of miR-136 in cervical carcinoma, and the miR-136/E2F1 axis acted important regulatory effects on cell proliferation." (PMID 33150164, 2020). "In cervical cancer, E2F1 expression is significantly increased suggesting that genes which are involved in invasive cervical carcinoma are regulated by E2F." (PMID 32157438, 2020). "The interaction between miR-136 and E2F1 has been documented in cervical carcinoma, and the miR-136/E2F1 axis played a functional role in the regulation of tumor cell proliferation." (PMID 33150164, 2020). "Real-time PCR and Western blot analysis revealed that mRNA and protein levels of NCAPH significantly decreased with the knockdown of E2F1 or increased with the over-expression of E2F1 in cervical cancer cells (all the p values < 0.05)." (PMID 33311486, 2020). "The Scotto Cervix dataset revealed that mRNA expression of E2F1 in cervical cancer tissue was 3.640 times higher than that found in normal cervical tissue (p = 1.23E−10)." (PMID 33061852, 2020). "For instance, miR-136 inhibits the proliferation of cervical carcinoma cells by targeting E2F1 and promotes the apoptosis through the NF-κB pathway." (PMID 32733928, 2020). "By analyzing the data from GEO database (GSE7803), we found that E2F1 expression was significantly increased from normal cervix to cervical cancer and from high-grade intraepithelial lesion (HSIL) to cervical cancer." (PMID 33311486, 2020). "Using multivariate analysis, we confirmed E2F1/2/7/8 as independent prognostic factors for shorter OS of patients with cervical cancer." (PMID 33061852, 2020). "FTO contributes to the proliferation and migration of cervical cancer cells by directly interacting with E2F1 and MYC transcripts and impairing their translation efficiency in a demethylase‐dependent manner." (PMID 33029866, 2020). "KAT2A knockdown leads to a significant reduction of DNA synthesis in cervical cancer cells by decreasing histone H3 acetylation in the E2F1 promoter." (PMID 31828117, 2019). "Our study indicates that FTO plays important oncogenic role in regulating cervical cancer cells’ proliferation and migration via controlling m6A modification of E2F1 and Myc transcripts." (PMID 31827395, 2019). "To confirm the function of RCC1 in the cell cycle, we treated SiHa cervical cancer cells with siRCC1s and observed downregulation of E2F1, Cdk1, and Cdk2 protein levels." (PMID 29789527, 2018). "It needs detailed investigation in cervical cancer cells to have a better understanding of the role of E2F1 in cervical cancer progression." (PMID 23773282, 2013). "In the context of cervical cancer, it has been reported that an overexpression of E2F1 can drive quiescent cells through G1 into S-phase of the cell cycle, ultimately leading to apoptosis or neoplastic transformation." (PMID 21696634, 2011). "On the other hand, there are reports of E2F1 and c-Myc overexpression in cervical cancer, which also correlate their expression with advanced states of the disease." (PMID 21696634, 2011). "Our results suggest a phenotype shared by the six cervical cancer cell lines as a result of the overexpression of c-Myc, helped by E2F1, which in turn allows the overexpression of 14-3-3ζ and other proteins of the "central core of cervical cancer"." (PMID 21696634, 2011). "Furthermore, they showed E2F transcription factor 1 (E2F1) promoted nc886 transcription and can promote drug resistance in cervical cancer cells by altering MVP expression." (PMID 37692527, 2024).
cervical carcinoma (continued). "Besides, circZFR bound with SSBP1, thereby inducing the assembly of CDK2/cyclin E1 complexes, which induced p-Rb phosphorylation, thus releasing activated E2F1 leading to cell cycle progression and cell proliferation in cervical cancer." (PMID 36008845, 2022). "Furthermore, a prior study highlighted that Ki67 expression was elevated in conjunction with E2F1 overexpression in cervical cancer, which reiterates the positive relationship between them." (PMID 35592867, 2022). "CircZFR could promote cervical cancer cell proliferation, migration, and invasion through the induction of p-Rb S807 and S608 phosphorylation and activating E2F1 signaling." (PMID 33516252, 2021). "Furthermore, E2F1, a cell cycle regulator, was described as a direct transcriptional regulator of vtRNA2-1 in cervical cancer cells (Liet al., 2017)." (PMID 34354812, 2021). "As a novel positive regulator of E2F1 signaling, circZFR may be a potential circulating biomarker with implications for the detection of cervical cancer." (PMID 33516252, 2021). "In conclusion, we demonstrated for the first time that HPV 18 E6/E7 could regulate MELK through transcription factor E2F1 in cervical cancer." (PMID 34671205, 2021). "CircRNA-ZFR, a novel positive regulator of E2F1 signaling, could be a potential biomarker for cervical cancer detection." (PMID 35186956, 2021). "Thus, leading to E2F1 transcription factor to express genes that promote entry into S-phase and promotes proliferation of cervical cancer." (PMID 33516252, 2021). "Furthermore, we showed that high expression of E2F1/2/7/8 proteins was significantly associated with shorter OS and DFS in patients with cervical cancer." (PMID 33061852, 2020). "In cervical cancer, high expression of E2F1/2/8 was observed in different datasets." (PMID 33061852, 2020). "For example, CAPE induces E2F-1-mediated growth inhibition in human cervical cancer cells." (PMID 29212221, 2017). "Inhibition of miR-17-5p and miR-20a in a cervical cancer cell line upregulates the E2F1 oncogene." (PMID 27765929, 2016). "Thus, our results suggest that CUL2 overexpression driven by CUL2/E2F1/miR-424 regulatory loop exists specifically in HPV16 infected cervical cancer cells." (PMID 27153550, 2016). "Furthermore, using ENCODE ChIP-seq data, we found that 32% of CHD8 target promoters were occupied by E2F1 in HeLa cells (P = 3.3 × 10−57), another cervical carcinoma cell line." (PMID 24265227, 2014). "Moreover, we demonstrate overexpression of circZFR promoted the p-Rb S807 and S608 phosphorylation and ac-E2F1 K117 and K125 acetylation using paired cervical cancer and normal tissues, which suggested that circZFR is a central upstream regulator in the activation of Rb-E2F1 signaling." (PMID 33516252, 2021). "Interestingly, the Rb/E2F1 pathway activating could promote cervical cancer progression by allowing the transcription of genes required for the G1-S phase transition and DNA replication." (PMID 35186956, 2021). "E2F1/2/7/8 may be prognostic biomarkers for survival of patients with cervical cancer." (PMID 33061852, 2020). "Similarly, ecotopic expression of E2F1 or Myc could significantly increase FTO competent cervical cancer cells’ migration compare to control cells." (PMID 31827395, 2019). "In cervical cancer, FTO interacts with E2F1 and MYC to increase its translation efficiency and promote cervical cancer cell migration and proliferation." (PMID 36360287, 2022). "Increased expression of E2F1/2/7/8 was also related to shorter overall survival (OS) and disease-free survival (DFS) in patients with cervical cancer." (PMID 33061852, 2020).
cervical carcinoma (continued). "Mechanistically, FTO directly interacted with E2F1 and Myc mRNAs and inhibition FTO dramatically impaired these two important oncogenes’ translation, thus suppressed cervical cancer cells’ proliferation and migration." (PMID 31827395, 2019). "Furthermore, E2F1-Chromatin immunoprecipitation (ChIP) specificity also showed that E2F1 suppression by E2F1 siRNA resulted in reduced E2F1 occupation on the miR-424 promoter Thus, our results suggest that E2F1 functions as a transcriptional repressor of miR-424 in cervical cancer cells." (PMID 27153550, 2016). "Our results indicate the existence of a regulatory loop among CUL2, E2F1, and miR-424 in HPV16 positive cervical cancer cells." (PMID 27153550, 2016). "HPV16 E7-CUL2 interaction recruits CUL2 and the activation of regulatory loop among CUL2, E2F1, and miR-424 produces the persistent CUL2 overexpression, which consequently promotes the growth of cervical cancer cells." (PMID 27153550, 2016). "We further verified that CUL2 bound to E2F1 and promoted E2F1 expression, and E2F1 was required for CUL2 mediated miR-424 inhibition in cervical cancer cells." (PMID 27153550, 2016). "In cervical cancer, GCN5 increases the binding of GCN5 to the E2F1 promoter region by acetylating c‐myc and increases the degree of histone acetylation in this region, accelerating E2F1 expression and cell cycle progression." (PMID 39778006, 2025). "In addition to our recent results showing that GCN5 upregulates E2F1 and thus promotes HPV E7 induced cell proliferation, the other roles of GCN5 in cervical cancer are still unclear." (PMID 32883234, 2020). "Additionally, interaction of FTO with E2F transcription factor 1 (E2F1) and MYC transcripts reduces m6A modification on the corresponding mRNA and enhances the translation efficiency of the mRNA, which is critical to the regulation of cervical cancer cell proliferation and migration." (PMID 32398132, 2020).
pancreatic cancer (47 papers, 2011 to 2026). "By Kaplan–Meier analysis on pancreatic cancer, the level of each gene is linked to survival probability, with high expression for E2F1, PRMT5 and cortactin/CTTN linked to poor survival." (PMID 32709847, 2020). "In conclusion, E2F1 promotes pancreatic cancer cell proliferation and cell-cycle progression by upregulating WDHD1, which in turn enhances the expression of the CDK4-cyclin D1 complex." (PMID 42041705, 2026). "Elevated STAMBP in pancreatic cancer has been found to interact with E2F1, preventing its degradation and promoting the PDK1-mediated Warburg effect, which contributes to chemotherapy resistance." (PMID 40149859, 2025). "One of the glucose transporter inhibitors, CG-5, reduces the expression of E2F1 and boosts the effectiveness of gemcitabine in pancreatic cancer cells." (PMID 36831413, 2023). "Taken together, these data suggested that ZNF655 facilitated malignant behaviors of pancreatic cancer cells via promoting the binding of E2F1 to CDK1 promoter." (PMID 35927248, 2022). "Mechanically, these data suggested that ZNF655 facilitated malignant behaviors of pancreatic cancer cells via promoting the binding of E2F1 to CDK1 promoter." (PMID 35927248, 2022). "In contrast, NDRs in primary pancreatic cancer-specific enhancers involved in enhancer-promoter loops are enriched for motifs for TFs such as E2F1, MAZ, and ZFX." (PMID 34348759, 2021). "Another study showed that knocking-down H19 impaired the viability and growth of pancreatic cancer cells by decreasing E2F1 expression." (PMID 34421359, 2021). "Together these data point at E2F1 as a regulatory factor modulating VMP1-mediated autophagy in human pancreatic cancer cells and integrate this degradative cellular process into the complex network of events involved in PDAC chemoresistance." (PMID 32655498, 2020). "The present paper reported that, in pancreatic cancer (PC) cells, E2F1, CCND1, CCNE1, and all members of the MCM2-7 family were downregulated after inhibition of the RPL21 expression, leading to the reduction of DNA replication." (PMID 33014855, 2020). "We demonstrated that E2F1 is able to induce autophagy in pancreatic tumor cells and regulates VMP1-mediated autophagy by a direct binding to VMP1 promoter." (PMID 32655498, 2020). "Even, down-regulation of EP300 impaired E2F1-mediated activation of the VMP1 promoter in pancreatic tumor cells." (PMID 32655498, 2020). "CG-5, a glucose transporter inhibitor, inhibits E2F1 expression and enhances gemcitabine efficacy in pancreatic cancer cells." (PMID 32122374, 2020). "Mechanistically, KLF5 promoted expression of E2F1, cyclin D1 and Rad51, while inhibiting expression of p16 in pancreatic cancer cells." (PMID 31327760, 2019). "Consistently, JMJD3 deficiency was reported to promote malignant progression of human pancreatic carcinoma by decreasing the expression of C/EBPα, a potential inhibitory partner of E2F1." (PMID 31665700, 2019). "Cdk4, Cdk6, E2F3, and E2F1 play key roles in the regulation of cell cycle progression in pancreatic cancer." (PMID 27613829, 2016). "Down-regulation of Cdk4, Cdk6, E2F3, and E2F1 expression increases G0/G1 cell cycle arrest in pancreatic cancer cells." (PMID 27613829, 2016). "In all four pancreatic cancer cell lines tested, we found decreased expression of cell cycleproteins, including E2F1, Cyclin D1, Cyclin E, Cdk2, Cdk4 and Cdk6, and increased expression of p21 and p27." (PMID 23028659, 2012). "In pancreatic cancer, it has been shown that E2F1 may induces aerobic glycolysis, here we link E2F1 expression in PDAC with expression of genes involved in the mitochondrial translation machinery." (PMID 38686617, 2024). "The E2F1-dependent pathway may also be adopted by pancreatic cancer cells treated with gemcitabine, but the exact mechanism is still unclear." (PMID 36831413, 2023).